PTX3 (pentraxin 3)
Diseases named in the same sentence as PTX3 in open-access papers (continued):
Sharing a sentence is not in itself a finding about the gene and the disease.
Sepsis (continued). "PTX3 behaves as an acute-phase protein, as its blood levels, low in normal conditions (<2 ng/ml in humans), increase rapidly in the plasma during inflammation (sepsis, endotoxin shock and other inflammatory conditions)." (PMID 21423699, 2011). "The biological role of PTX3 in bacteremia and sepsis calls for further elucidation." (PMID 21423699, 2011). "Additionally, greater levels of PTX3 are related to the progress of septic shock and severe sepsis." (PMID 39762781, 2025). "Future research should focus on refining the role of PTX-3 in different etiologies of sepsis and evaluating its potential as a therapeutic target, such as whether the PTX-3 level can guide the use of antibiotics, etc., and its molecular biological mechanism still needs to be further clarified." (PMID 39021820, 2024). "Furthermore, we found that the protein expression levels of Bax, Caspase-3, and Caspase-9 were significantly lower, and the protein expression levels of Bcl-2 were significantly higher in Group B. These results indicate that PTX3 inhibits the apoptotic ability of cardiomyocytes in sepsis." (PMID 38784395, 2024). "Consequently, this investigation delves into the apoptosis and autophagy engendered by the PI3K/AKT/mTOR axis through both in vivo and in vitro studies, and provides an exhaustive portrait of PTX3’s influence on myocardial injury in sepsis and its underpinning mechanisms." (PMID 38784395, 2024). "It raised the question of whether PTX3 can be used as a tool in sepsis for early detection." (PMID 36168379, 2022). "To estimate the prognostic value of these potential biomarkers, we created Kaplan–Mayer survival curves for the incidence of sepsis mortality during 90 days follow-up, comparing under and over cut-off values for the candidate indicators including PTX3, PCT, lactate, and platelet count." (PMID 34679604, 2021). "In sepsis, PTX3 may serve as an early marker of the severity and outcome of the disease." (PMID 33912155, 2021). "To investigate whether any single or combined biomarkers could be used to discriminate sepsis and septic shock, we included PTX3 and other positive biomarkers, such as PCT, lactate, and platelet count, in the univariate and multivariate logistic regression analysis." (PMID 34679604, 2021). "Thus, the present study aimed to investigate the diagnostic and prognostic values of circulating PTX3 among sepsis patients with or without septic shock and critically ill patients at the first 24 h of admission following Sepsis 3.0 definitions." (PMID 34679604, 2021). "Furthermore, using murine models of endotoxemia and multiplexed proteomics, we assessed the contribution of key oxidant-generating enzymes in the regulation of PTX3 multimerization and reveal that vascular deposition of PTX3 in response to sepsis is neutrophil dependent." (PMID 33288685, 2021). "Moreover, PTX3 dysregulation plays an important roles in cancer development and sepsis." (PMID 32436939, 2020). "In the present study, using whole blood of sepsis patients and healthy volunteers (HV) as well as an in vitro model that mimics immune alterations found in patients, we examined the transcriptomic and proteomic changes of PTX3 upon ex vivo stimulation challenge." (PMID 30687307, 2018). "However, in critically ill patients, PTX3 was no better than CTpr as a diagnostic index of infection and sepsis." (PMID 25530683, 2014). "PTX3 may thus be used as an early biomarker in sepsis patients." (PMID 23341967, 2013). "Moreover, PTX3 was shown to be increased with increasing disease severity from SIRS to sepsis." (PMID 24039869, 2013). "New screening tools such as Presepsin (sCD14-ST), PTX3, nCD64, and Monocyte Distribution Width (MDW) have shown potential in improving sepsis detection." (PMID 40123668, 2025). "Thus, PTX3 could be a potential prognostic indicator and therapeutic target in sepsis." (PMID 39666228, 2024).
Sepsis (continued). "Another study assessed the clinical significance of IL-6, PTX-3, and PCT in patients with sepsis and septic shock." (PMID 39201697, 2024). "In the study of sepsis-induced acute kidney injury (AKI) in critically ill patients, PTX-3 was identified as a key marker of inflammation and tissue damage." (PMID 39201697, 2024). "A study evaluated the clinical utility of IL-6, PTX3, and PCT in patients with sepsis and septic shock by measuring the serum concentration of these markers in 142 subjects." (PMID 39201697, 2024). "In addition, measurement of PTX3 in combination with cytokine levels (IL-6 and IL-18), and other routine clinical parameters rapidly available in ED (e.g., age, urea), can provide a promising approach for 90-days mortality prediction for sepsis patients, better than the use of a single biomarker." (PMID 36189302, 2022). "PTX3 is also correlating significantly with PCT and lactate, biomarkers found to be effective in sepsis for ages." (PMID 36168379, 2022). "In addition to being a more reliable measure of illness severity in cases of sepsis, PTX3 levels, in combination with other coagulation function assays, such as platelet count, PT, and aPTT, may also be beneficial in identifying patients in need of anticoagulation medications." (PMID 35449688, 2022). "Thus, PTX3 may be an independent predictor of bad outcomes in sepsis." (PMID 34679604, 2021). "Using a stepwise multivariate analysis, we screened out a combination of PTX3 and PCT to increase the specificity of diagnosis and severity stratification, correctly identifying 68.2% sepsis patients and correctly classifying 69.3% septic shock patients." (PMID 34679604, 2021). "First, we investigated the prognostic value of individual biomarkers (PTX3, PCT, IL6, and lactate) or their combination in patients diagnosed with sepsis or septic shock according to the latest Sepsis-3 definitions." (PMID 32481464, 2020). "In recent years, pentraxin 3 (PTX3), an acute phase protein, has emerged as a promising biomarker of sepsis." (PMID 33301518, 2020). "We aimed to conduct a prospective observational analysis to confirm the prognostic value of PTX3, PCT, IL6, and lactate in patients with sepsis or septic shock." (PMID 32481464, 2020). "The results showed that plasma PTX3, MCP1 and Ang2 significantly increased in patients on the first day of septic shock onset, while sepsis patients had significantly higher Ang2 level, compared with controls." (PMID 31489646, 2019). "Pentraxin 3 (PTX3), which belongs to the long pentraxin family, is expressed in a variety of cells during various inflammatory processes, including sepsis." (PMID 31718563, 2019). "In a prospective analysis, the changes in plasma levels of PTX3, PCT and lactate during the first week in ICU stay were compared to severity scores of sepsis (SOFA and APACHE II)." (PMID 31031772, 2019). "Collectively, our data revealed that PTX3, MCP1 and Ang2 were highly upregulated in the plasma of sepsis, and the expression strongly correlated with the severity of sepsis." (PMID 31489646, 2019). "Thus, PTX3 could complement the system of classification of the disease, contributing to define a group of useful biomarkers and strengthening their use in the diagnosis and monitoring of sepsis and septic shock." (PMID 31031772, 2019). "Serum levels of IL-6, PTX3, and PCT were measured in 142 enrolled subjects (51 with sepsis, 46 with septic shock, and 45 as controls)." (PMID 31718563, 2019). "Pentraxin-3, along with other biomarkers such as PCT and lactate, have been stated as clinically informative of disease severity and patient outcome in sepsis and septic shock." (PMID 30687307, 2018). "The prognostic value of PTX3 in our cohort was better than that for PCT and lactate during the first days once diagnosed with sepsis." (PMID 29435167, 2018).
Sepsis (continued). "Hence, altered immune cells still have the ability to produce PTX3 in response to an inflammatory trigger, and therefore circulating white blood cell subset could be responsible of the sustained PTX3 plasma levels over the first days of sepsis setting." (PMID 30687307, 2018). "The study evaluated the accuracy of PTX3, PCT and lactate, and their combinations, as biomarkers of severity and prognosis of patients with sepsis/septic shock." (PMID 29435167, 2018). "Moreover, PTX3 is described as induced by TNFα but TNFα signaling pathway is known to be disrupted in sepsis which suggests that PTX3 may be induced through other signaling pathways especially if PTX3 has a major anti-inflammatory effect in sepsis." (PMID 30687307, 2018). "Eleven papers on original studies of critically ill patients that report on PTX3 in SIRS, sepsis, or bacteremia were identified." (PMID 25530683, 2014). "But the study of patients with SIRS showed that PTX3 and CRP had similar performance in discriminating between SIRS and sepsis." (PMID 25530683, 2014). "High PTX3 and PCT were independent predictors for severe sepsis between day 0 and 28 and case fatality on day 28 after admission." (PMID 23341967, 2013). "PTX3 values proved to be significantly elevated in patients with SIRS and sepsis compared to healthy controls." (PMID 24039869, 2013). "Both PTX3 and PCT remained independent predictors for severe sepsis and case fatality also after adjustment for potential confounders whereas high CRP did not." (PMID 23341967, 2013). "Comparison of these groups showed that PTX3 is a good at discriminating healthy controls from patients with SIRS and sepsis since the ROC analysis showed that the assay was highly specific and sensitive." (PMID 24039869, 2013). "Multivariate logistic regression analysis evaluating the independent predictive value of pentraxin 3 (PTX3), procalcitonin (PCT) and C-reactive protein (CRP) for severe sepsis." (PMID 23341967, 2013). "In conclusion, we have established a highly sensitive and robust assay for measurement of PTX3 and found that its serum concentrations correlated with disease severity and mortality in patients with SIRS and sepsis." (PMID 24039869, 2013). "The optimal cut-offs for PTX3, PCT and CRP in predicting severe sepsis between day 0 and day 28 and case fatality were estimated using ROC curves and Youdeńs index." (PMID 23341967, 2013). "In a univariate model high PTX3, PCT and CRP values predicted severe sepsis when used as continuous or grouping variables." (PMID 23341967, 2013). "The validity of this new assay was shown when we investigated the use of PTX3 as biomarker in patients with SIRS and sepsis compared with controls, which consisted of randomly selected Danish blood donors." (PMID 24039869, 2013). "We prospectively studied pentraxin 3 (PTX3), a soluble innate immunity receptor, and clusterin (CLU), a chaperone protein that binds extracellular histones during sepsis, in patients experiencing febrile neutropenia after intensive treatment for haematological malignancies." (PMID 40722110, 2025). "At D0 (day of fever onset), serum PTX3 levels were higher in patients with severe sepsis than in patients with fever without sepsis (p = 0.02)." (PMID 40722110, 2025). "While PTX-3 is not yet included in the major sepsis guidelines, such as the SSC guidelines, ongoing research supports its potential utility as a sepsis biomarker." (PMID 39201697, 2024). "Collectively, our findings show that the absence of Ptx3 can ameliorate sepsis-induced liver injury by regulating hepatocyte ferroptosis and promote the recruitment and polarization of M1 macrophages." (PMID 39666228, 2024). "Other sepsis markers including miRNAs, sTREM-1, and Pentraxin-3 (PTX3) were also not examined in our study due to financial constraints." (PMID 37189528, 2023).
Sepsis (continued). "In this meta-analysis, the pooled results from 11 studies found that the level of PTX3 was significantly higher in non-survivors of sepsis compared to survivors, which also indicates that survivors are lower values." (PMID 35676730, 2022). "These molecules have also been found to be increased in patients with other infectious or chronical diseases such as sepsis, HIV-1-AIDS, tuberculosis, rheumatoid-arthritis and various cancers with suPAR, sEPCR and PTX3, often predicting poor clinical outcomes as in our present study." (PMID 35204613, 2022). "At ED arrival, a progressive increase in the circulating levels of PTX3, sIL-1R2 and both pro- and anti-inflammatory cytokines was observed from non-sepsis to sepsis and septic shock patients." (PMID 36189302, 2022). "Our meta-analysis suggested that serum PTX3 levels in non-survivors with sepsis were higher than in survivor patients." (PMID 35676730, 2022). "Our meta-analysis suggested that plasma PTX3 concentration was significantly higher in non-survivor compared to survivor patients with sepsis." (PMID 35676730, 2022). "A combination between PTX3 and procalcitonin (PCT) could better discriminate sepsis and septic shock, and PTX3 was an independent predictor of mortality in sepsis and septic shock patients." (PMID 34679604, 2021). "Some other molecules proposed as ideal predictor biomarkers of sepsis include CD64, the soluble receptors of myeloid cells (sTREM)-1, the soluble urokinase-type plasminogen activator receptor (suPAR), and pentraxin-3, but they are still far from application in the ED." (PMID 34577843, 2021). "Compared with other indicators, PTX3 showed more specificity in differentiating septic shock patients from non-shock sepsis patients (cut-off value: 11.12 ng/mL), higher AUC-ROC values, and more stable and accurate (using LOOCV test)." (PMID 34679604, 2021). "Given this, although PTX3 did not perform the best in distinguishing sepsis patients from other critically ill patients, it should not be excluded for the application of auxiliary diagnosis and prediction in routine clinical settings." (PMID 34679604, 2021). "In addition, CAP patients without sepsis displayed similar levels of plasma host response biomarkers compared to CAP patients with sepsis, with the exception of modestly higher levels of pentraxin-3, resistin, NGAL and sVCAM-1 in CAP patients with sepsis." (PMID 32477337, 2020). "In sepsis and septic shock, PTX3 discriminates from healthy controls, and non-survivors consistently show levels higher than survivors." (PMID 31031772, 2019). "In other words, in patients with severe sepsis, PTX3 serum levels decline slower than in those without severe sepsis." (PMID 31798002, 2019). "Moreover, PTX3, MCP1 and Ang2 had high AUROC values in patients with septic shock on the first day of sepsis onset." (PMID 31489646, 2019). "This study enrolled patients from the ICU and did not assess the prognostic value of PTX3 in sepsis." (PMID 31718563, 2019). "The findings suggest that PTX3, MCP1 and Ang2 maybe early predictors to evaluate the severity of sepsis and septic shock with the latest Sepsis 3.0 definitions." (PMID 31489646, 2019). "In a small cohort of critically ill patients, Mueller and co-workers observed increased PTX3 plasma levels compared to healthy control donors, with a gradient from SIRS to sepsis and septic shock, and a significant correlation with disease severity as assessed by clinical scores." (PMID 31031772, 2019). "Finally, a study in a small group of preterm infants showed a correlation between PTX3 levels in newborns and overall worsen neonatal outcome (i.e., lower APGAR score, elevated respiratory distress syndrome rate, clinical sepsis, and prolonged NICU stay)." (PMID 31031772, 2019). "Furthermore, PTX3, MCP1 and Ang2 had high AUROC values in patients with septic shock on the first day of sepsis onset." (PMID 31489646, 2019).
Sepsis (continued). "We then investigate the dynamic change of PTX3, PCT and lactate in patients with sepsis during the first week in ICU stay and perform a comparison with well-established scores, such as Sepsis-related Organ Failure Assessment (SOFA) and Acute Physiology and Chronic Health Evaluation (APACHE II)." (PMID 29435167, 2018). "we found that combining PTX3, PCT and lactate, named PPL, significantly improved the performance of these markers along and better than both SOFA and APACHE II scores in predicting in-hospital mortality of adult sepsis." (PMID 29435167, 2018). "In summary, our results suggest that PTX3, PCT and lactate could serve as clinically informative biomarkers of disease severity and patient outcome in sepsis/septic shock." (PMID 29435167, 2018). "PTX3, PCT are specific for different aspects of the inflammatory process leading to sepsis." (PMID 29435167, 2018). "We and others all showed PTX3 concentrations were quickly reduced during the ICU stay with effective treatment, which may indirectly reflect the severity of sepsis at the onset then to predict the outcome." (PMID 29435167, 2018). "PTX3 has been recognized as a reliable prognostic marker of not only CVD but also sepsis, infectious disease, and a shock state, in all of which a significant correlation has been found between PTX3 plasma levels and disease severity." (PMID 27559483, 2016). "Systemic levels of PTX3 have prognostic value and may add to prognostication of patients with SIRS or sepsis, complementing severity-of-disease classification systems and other biological markers." (PMID 25530683, 2014). "Plasma PTX3 levels have recently been found to be elevated in patients with vasculitis, acute myocardial infarction, and systemic inflammation or sepsis, however, there is no information about changes in PTX3 levels in NAFLD or NASH patients." (PMID 19014569, 2008). "Interestingly, the inhibition of Ptx3 influenced CCR5 expression in the absence of LPS induced sepsis." (PMID 39666228, 2024). "However, few studies showed that pentraxin 3, compared to procalcitonin and CRP, did not have a diagnostic advantage in predicting sepsis in clinical practice." (PMID 35449688, 2022). "PTX3 and sIL-1R2 levels at day 1 and day 5 in non-sepsis, sepsis and septic shock patients." (PMID 36189302, 2022). "PTX3 level was significantly higher in non-survivor compared to survivor patients with sepsis." (PMID 35676730, 2022). "Besides, the serum concentrations of PTX3 were dramatically raised in non-survivors compared to that in survivors (p < 0.001) in patients diagnosed with sepsis." (PMID 34679604, 2021). "Similarly, a cardiac tissue proteome study reported that the oligomerization of pentraxin-3 (PTX-3) increased in patients who did not survive sepsis." (PMID 33425215, 2020). "This study investigated the clinical value of interleukin-6 (IL-6), pentraxin 3 (PTX3), and procalcitonin (PCT) in patients with sepsis and septic shock diagnosed according to the Third International Consensus Definitions for Sepsis and Septic Shock (Sepsis-3)." (PMID 31718563, 2019). "Furthermore, PTX3, MCP1 and Ang2 maybe early predictors to evaluate the severity of sepsis and septic shock according to the latest Sepsis 3.0 definitions." (PMID 31489646, 2019). "In this study, we addressed that multi-marker approach may be an aid for the prognosis prediction and conducted multivariate logistic regression to obtain a new sepsis score PPL (PTX3 + PCT + lactate), which yielded better prognostic value than PTX3, PCT or lactate alone." (PMID 29435167, 2018). "This could explain why PTX3 was not altered during sepsis and can still be secreted over the course of the disease." (PMID 30687307, 2018). "Pentraxin 3 (PTX3), which is produced by endothelial cells in response to various inflammatory events, has been proposed as an indicator of inflammatory vascular injury and as a biomarker of vasculitis in SLE and other diseases such as sepsis, septic shock, and preeclampsia." (PMID 28546658, 2017).